INS (insulin)
Diseases named in the same sentence as INS in open-access papers (continued):
Sharing a sentence is not in itself a finding about the gene and the disease.
Obesity (continued). "Administration of GSK-3 inhibitors to rodent models of obesity and T2DM have consistently improved insulin sensitivity and glucose homeostasis." (PMID 35159367, 2022). "The isolated WAT/BAT from obese and insulin-resistant rodents and humans had lower AMPK activity, which was enhanced by obesity therapy." (PMID 35996069, 2022). "BAIBA is a novel protective myokine that is increased during exercise via a PGC1α-dependent mechanism, improves insulin sensitivity, and protects against HFD-induced obesity." (PMID 35563026, 2022). "We demonstrate, using two types of viral vectors and two different mouse models of obesity, a novel metabolic role for adipose-derived LRG1 as a regulator of glucose homeostasis by promoting insulin sensitization." (PMID 36346018, 2022). "Prepubertal girls with obesity had significantly higher values (p < 0.05) for BMI-SDS, leptin, insulin and HOMA-IR levels than control group." (PMID 35412268, 2022). "In our study, in addition to the result that leptin was found to positively correlate with all obesity markers, OB subjects had higher insulin and HOMA-IR values compared to NW subjects, and a positive correlation was seen between leptin, insulin and HOMA-IR." (PMID 36355134, 2022). "The GTT and ITT data in the present study revealed that STM treatment significantly promoted obesity-associated glucose tolerance and insulin sensitivity, although overnight fasting may not be optimal in our GTT test and a short time (4‒6 h) fasting may be more appropriate." (PMID 36305727, 2022). "For experimental research on T2DM, a HFD-induced obesity-dependent T2DM mouse model was developed, which reduced insulin sensitivity, resulting in overproduction of glucose." (PMID 35052549, 2021). "JAZF1 overexpression in transgenic mice improved insulin sensitivity and protected HFD-induced obesity." (PMID 34407873, 2021). "Overall, our study suggests that maternal obesity induces sex-specific changes to pancreatic HSG in offspring and a lasting effect on offspring insulin secretion, leading to the sex-differences in glucose intolerance." (PMID 34108935, 2021). "Insulin and IGF signaling combined with chronic inflammation are also important factors for obesity, promoting CRC development." (PMID 34422629, 2021). "We previously showed that obesity-prone HFD-fed dams have higher serum NEFA, glucose and insulin levels." (PMID 33903707, 2021). "IR is the consequence of obesity which is seen in CAV1 knock-out mice and is consistent with the medical descriptions of overweight and obese subjects by showing decreased insulin sensitivity in adipose tissues." (PMID 34001235, 2021). "Despite an increased prevalence of obesity being observed in both HFD-contained groups, adipose IL-1β inflammation and insulin resistance were significantly lower in MUFA-HFD mice compared with the SFA-HFD group." (PMID 34206632, 2021). "Alongside improvements in PVAT function, these studies also demonstrated improvements in insulin sensitivity and blood pressure, highlighting the importance of restoring PVAT function to treat the vascular complications of obesity." (PMID 33687595, 2021). "Thus, Epac2A seems to play a role in insulin secretion induced by the combination of an incretin and SU, especially in a model of diet-induced obesity, and may provide an explanation for the SU-dependent difference in the incidence rate of hypoglycemia observed in combination therapies." (PMID 34359828, 2021). "Usually, obesity may be responsible for the Gn resistance during ovarian stimulation according to the previous research, possibly due to the overstimulation of ovarian steroidogenesis and decrease of sex hormone-binding globulin blood concentrations mediated by insulin." (PMID 34584537, 2021). "GPR91deletion in myeloid cells protected mice from obesity on HFD, but these mice showed impaired glucose tolerance and insulin sensitivity." (PMID 34943862, 2021).
Obesity (continued). "In obesity, proinflammatory immune cells, such as interferon (IFN)-γ+T helper type 1 cells and CD8+T cells, are elevated, with reduced secretion of insulin-sensitizing adiponectin in AT." (PMID 33671547, 2021). "Infusion of 180 mmol/L acetate in men with overweight and obesity affected whole-body metabolism, as measured by the increase in fasting fat oxidation, PYY, and postprandial insulin and glucose levels." (PMID 34684670, 2021). "In conditions of obesity, DMT2, and insulin resistance, vasoconstriction seems to also involve the adipose tissue, resulting in blunted post prandial adipose tissue perfusion, low blood flow, hypoxia, and increased inflammation." (PMID 33668627, 2021). "The most frequently ordered metabolic screening tests for patients with obesity and PCOS among all the participants were fasting glucose and fasting insulin tests (78.5%), followed by OGTT (59.8%) and lipid profile (46.2%)." (PMID 34488736, 2021). "tFNAs-RSV notably improved insulin sensitivity in HFD-fed mice by targeting inflammation, breaking the links between obesity and IR." (PMID 34138319, 2021). "According to the current findings, it is known that the pivotal targets of acupuncture for improving obesity are mainly focused on the neurons or neuropeptides in the hypothalamic ARC, the peripheral hormones (leptin and insulin)." (PMID 33868169, 2021). "The administration (20 mg/kg/day) to diet-induced obesity mice was able to reduce decrease fasting blood glucose (FBG) and insulin levels, and enhanced glucose tolerance and insulin sensitivity." (PMID 33981219, 2021). "Finally, CD24 KO male mice may serve as a model of obesity and insulin hyper-sensitivity." (PMID 33467499, 2021). "Pancreatic β-cells are among the most affected cells, whose impaired insulin secretion results in the development of insulin resistance, T2DM or other obesity-related pathologies, such as cardiovascular diseases and the metabolic syndrome." (PMID 34206632, 2021). "This study shows that lower levels of blood glucose and insulin were observed in the HFD-fed group with TFP treatment than those detected in HFD-fed animals receiving Vehicle, suggesting that TFP and TFP-like agents may hold potential for the treatment of obesity-associated hyperglycemia." (PMID 34764855, 2021). "Hypermetabolic obesity-hyperinsulinemia (HMO-I, 8% patients) was distinguished by overcompensated insulin secretion and a large increased incidence of polycystic ovary syndrome (AOR 14.44 to MHO, 95%CI 1.75-118.99)." (PMID 34335479, 2021). "The role of HSR in insulin sensitivity has been recently demonstrated, since HSP70 was shown to protect against high-fat-diet- and obesity-induced hyperglycemia, hyperinsulinemia, glucose intolerance and insulin resistance." (PMID 34299993, 2021). "Dietary CHO and excess secretion of insulin play a major role in the accumulation of BF, which is referred to as the CHO-insulin model of obesity." (PMID 33922998, 2021). "Obesity, MGUS, and MM share common etiopathogenesis mechanisms including altered insulin axis and the action of inflammatory cytokines." (PMID 33531904, 2021). "This approach revealed that patients with lower levels of VITD and obesity class II or III tend to present a distinct profile hallmarked by higher values of HbA1c, FPG, Cholesterol, LDL, triglycerides, TSH, insulin and HOMA-IR." (PMID 34578857, 2021). "Finally, the elevated insulin and leptin levels in children with obesity might promote growth." (PMID 34386750, 2021). "Obesity and T2DM are often accompanied by insulinemia; long-term stimulation with high insulin induces the activation of Egr-1 in hepatocytes and reduces the regulatory effect of insulin." (PMID 33880382, 2021). "Xenin is known to potentiate the actions of GIP, and in addition to positive glycaemic outcomes, through reduced appetite and augmented insulin secretion, the peptide also restored GIP sensitivity that is dampened in obesity." (PMID 34093449, 2021).
Obesity (continued). "In conclusion, DOP can improve insulin sensitivity by up-regulating the expression of PPAR-γ, thus improving obesity-related IR." (PMID 34194325, 2021). "CD24 KO male mice displayed, at an early age, greater insulin sensitivity and glucose uptake, suggesting a gender-dependent role of CD24 in insulin-sensitive obesity." (PMID 33467499, 2021). "It seems that foods can induce postprandial insulin secretion and affect the management of hyperlipidemia, CVD, obesity, and DM11." (PMID 34354158, 2021). "Together, these results demonstrate that the development of obesity in IRF3 KO mice is accompanied by increased M1 macrophage infiltration and WAT inflammation, which contributed to impaired insulin sensitivity." (PMID 34091599, 2021). "For example, the effects of increased levels of insulin and insulin-like growth factor-1 (IGF-1) in obesity have been investigated in primary intestinal epithelial crypts isolated from obese humans." (PMID 34659571, 2021). "Other critical modulators of the obesity phenotype exist within the ATP2A1 locus, such as SH2B1, a gene involved in leptin and insulin signaling." (PMID 34489471, 2021). "Capsaicin also reduces the inflammation that is induced by obesity by decreasing TNF-α, IL-6, IL-8, and MCP-1 levels, and elevating adiponectin levels, which are important for the insulin response." (PMID 33670130, 2021). "In diet-induced obesity and metabolic disorders, IFN-γ reduced insulin signaling and lipid storage in fat cells." (PMID 33500717, 2021). "Peripheral insulin sensitivity (total and adjusted per FFM) decreased across the spectrum of glycemia in the groups with obesity and was significantly lower than that of the NW group." (PMID 33616083, 2021). "APs can adversely impact metabolic function through direct effects on lipids and insulin sensitivity and indirect effects on these parameters as a result of AIWG and obesity." (PMID 33776816, 2021). "For instance, ERK modulates inflammatory activation of macrophages to inhibit beige adipogenesis in obesity, p38 regulates inflammation and insulin signaling, JNK promotes obesity-induced IR by regulating ATMs M1 polarization in WAT." (PMID 34393781, 2021). "Therefore, it might be hypothesized that the described anorexigenic feedback mechanism associated with BDNF signaling is attenuated in patients suffering from obesity, comparable with the insulin or leptin resistance as a consequence of long-lasting overeating in patients suffering from obesity." (PMID 33367955, 2021). "Myeloid-specific ANT2-knockout (ANT2-MKO) mice showed decreased adipose tissue inflammation and improved insulin sensitivity and glucose tolerance in HFD/obesity." (PMID 34676827, 2021). "Overall, the “incretin effect” has been reported to be decreased in obesity, likely as a result of a reduced responsiveness to GIP or reduced contribution of GLP-1 to the insulin secretory response." (PMID 33671882, 2021). "Overweight/obesity was observed in 90% of adolescents with increased HOMA-IR, and in 91% of those with increased insulin levels." (PMID 35053629, 2021). "This is the first study to demonstrate a positive association between insulin treatment in pregnancy among women with obesity and reduced PPD rates, suggesting insulin as a possible preventative measure." (PMID 33743677, 2021). "Patients receiving SGLT2 inhibitors were more likely to have high levels of hyperlipidemia and obesity and to be simultaneously receiving GLP-1 agonists, insulin, metformin, and statins compared with those receiving DPP4 inhibitors." (PMID 34797368, 2021). "In this review, we will analyze LEAP-2’s effects from a metabolic point of view with a focus on metabolic hormones (e.g., ghrelin, GH, and insulin), and discuss LEAP-2’s potential as a promising therapeutic target for obesity." (PMID 34512549, 2021). "Level of insulin and HOMA-IR were significantly higher in patients with T2DM+obesity+CP vs patients with only T2DM, respectively by 4.20 and 4.64 times (p<0.001)." (PMID 35221617, 2021).
Obesity (continued). "Serum leptin, insulin, and HOMA-IR were significantly elevated in with obesity compared to normal-weight groups during childhood." (PMID 34386750, 2021). "This pathway is stimulated by insulin, insulin-like growth factor 1 (IGF-1), exercise, and testosterone, all of which decrease with obesity and aging." (PMID 34676021, 2021). "Several mechanisms have been proposed in obesity, including inflammation, oxidative stress, insulin resistance, altered lipid and cholesterol homeostasis, which may result in neuroinflammation, altered brain insulin signaling, amyloid-beta (Aβ) deposition and neuronal cell death." (PMID 34690698, 2021). "It was demonstrated that PTP1B knockout mice displayed enhanced insulin sensitivity and IRP phosphorylation, being resistant to high-fat diet (HFD)-induced obesity." (PMID 34732209, 2021). "Chronic hypersecretion of stress mediators, such as glucocorticoids, may result in insulin and leptin hypersecretion, contributing to insulin and leptin resistance, along with dysregulation of appetite and food intake by inducing alterations in the reward system, finally leading to obesity." (PMID 33800718, 2021). "In the presence of inflammation and obesity, the increased expression of STAMP2 has protective effects against insulin signaling in the liver." (PMID 34497643, 2021). "First of all, glucose uptake is essential for the thermogenesis process and, in a state of obesity, pro-inflammatory signaling can alter BAT insulin sensitivity through a complex TNFα-mediated mechanism." (PMID 33805912, 2021). "The various pathophysiological mechanisms that lead to depression are Insulin resistance, disturbance in the hypothalamic pituitary adrenal (HPA) axis, hyperandrogenism and its clinical presentation, obesity, and infertility." (PMID 34667688, 2021). "Thus, we hypothesized that insulin treatment will reduce the risk of PPD among women with obesity to the level of risk seen among women without obesity." (PMID 33743677, 2021). "In obesity, PVAT loses its dilator and anti-inflammatory actions, leading to a proinflammatory state which promotes vasculature insulin resistance, impairs insulin vasodilation NO dependent, and leads to vascular dysfunction." (PMID 33668627, 2021). "It was reported that PTX3 mRNA expression is upregulated in visceral adipose tissue in obesity, whereas the plasma PTX3 levels inversely correlated with insulin secretion." (PMID 33594624, 2021). "It was implied that BRS were effective on reducing LEP and INS levels, increasing ghrelin and ADP levels, and then inhibiting obesity." (PMID 33585429, 2021). "We demonstrate an insulin- and leptin-resistant phenotype in IIH in excess of that driven by obesity." (PMID 33848268, 2021). "SCFAs appear to have a complex and pleiotropic role in obesity; on one hand, SCFAs may enhance energy harvest and contribute to excess lipogenesis in the liver, but also concurrently reduce inflammation, sensitize tissues to insulin, contribute to satiety and improve gut barrier function." (PMID 34222034, 2021). "In chronic inflammation state of obesity, IFN-γ signaling restricts expansion of white adipose tissue (WAT) and decrease insulin sensitivity." (PMID 33482868, 2021). "Therefore, various biopharmaceutical engineering approaches may be adopted to develop IGFBP2 analogues and mimetics with improved physiological properties in obesity and insulin sensitivity, pharmacokinetic profiles and potency that are suitable for future clinical development." (PMID 33498859, 2021). "Also, whole-grain consumption has the effect of prolonged satiety and also the capacity to slow down starch digestion and absorption and may as well lead to lower glucose and insulin responses, and the prevention of obesity, which are beneficial conditions for reducing the development of MetS." (PMID 33731080, 2021).
Obesity (continued). "Overall, our findings are in accordance with accumulating evidence suggesting the possible regulatory role ofmiRs in multiple processes involved in obesity, including pAds ADG and insulin sensitivity." (PMID 34299331, 2021). "In a mouse model of diet-induced obesity, SCOPA diet supplementation lowered fasting insulin and glucose levels, while inducing metabolically favorable changes in adipose tissue and liver." (PMID 35211087, 2021). "In this sense, the GSTA4 expression is down regulated in the adipose tissue from obese insulin- resistant C57BL/6 mice and in humans with obesity and IR." (PMID 33916540, 2021). "As important regulators of blood glucose and lipid metabolism, insulin and IGF also play an important role in the progress of obesity related tumors." (PMID 34485124, 2021). "Further evidence from literature suggests that increased expression of miR-26a, decreases glucose stimulated insulin secretion (GSIS), thereby reducing hyperinsulinemia, a contributor in diabetes and obesity." (PMID 34690698, 2021). "Although the role of insulin and IGF-1 in regulating metabolism in response to nutrients is well known, the role of IGF-1 in obesity mechanisms and IR is less described." (PMID 34208601, 2021). "Moreover, it is also important to stress that hyperinsulinemia in obesity impairs insulin sensitivity in the brain, leading to deregulation of food intake and eventually body weight gain that may also contribute to the aggravation of the obese phenotype in BKO mice challenged with HFD." (PMID 34015524, 2021). "Both IPGTT and ITT confirmed glucose metabolic imbalance in obesity, including increased fasting blood glucose (FBG), impaired glucose tolerance, and decreased insulin sensitivity." (PMID 34899326, 2021). "Having established that hepatocyte depolarization increases serum insulin concentrations, and that the hepatic vagus is essential for diet-induced hyperinsulinemia, we next hypothesized that hepatocyte hyperpolarization would prevent obesity-induced hyperinsulinemia." (PMID 34192533, 2021). "Notably, the metabolic outcomes of ageing and diet-induced obesity in mice are different, with ageing resulting in increased insulin secretion and ultimately improved glucose tolerance in advanced age mice, whereas diet-induced obesity progressively impairs insulin secretion and glucose tolerance." (PMID 33622333, 2021). "Further, the serum level of MG53 is upregulated in obesity and T2DM, and administration of MG53 was found to inhibit the insulin response in multiple organs." (PMID 34440850, 2021). "For this purpose, we analyzed the anorexigenic response to leptin and the hypothalamic insulin signaling after two weeks of HFD, before the onset of obesity." (PMID 34015524, 2021). "PSCs are activated in obesity and hyperglycaemic states through various mechanisms, such as inflammation, oxidative stress, MAP kinases activation, and insulin signalling." (PMID 34769147, 2021). "In studies using an insulin lowering agent, dapagliflozin, a sodium-glucose cotransporter-2 (SGLT2) inhibitor, reduction in insulin levels slowed obesity-accelerated tumor growth of both syngeneic breast and colon cancer models." (PMID 33987528, 2021). "Ablation of OGT, and thus O-GlcNAcylation, in skeletal muscle (mKO) resulted in increased energy expenditure, improved insulin sensitivity, protection against HFD-induced obesity, and dysregulation of muscle interleukin-15 (Il15) expression." (PMID 34326778, 2021). "IR underpins both obesity and T2DM, since it impairs cellular response to insulin affecting carbohydrate, lipid, and protein metabolism, and resulting in high blood glucose levels." (PMID 35221617, 2021). "Indeed, obesity-related pathological consequences, such as insulin and leptin resistance, mitochondrial dysfunction and ROS production, may anticipate and accelerate the physiological aging processes that involve also higher susceptibility to neurodegenerative diseases." (PMID 32825115, 2020).